PHEX (phosphate regulating endopeptidase X-linked)
Diseases named in the same sentence as PHEX in open-access papers (continued):
Sharing a sentence is not in itself a finding about the gene and the disease.
hypophosphatemia (37 papers, 2012 to 2025). Lower than normal levels of phosphates in the circulating blood. "Regarding the pathogenic mechanism, the influence of the PHEX gene variant on height is not only related to abnormal bone mineralization caused by hypophosphatemia, but also associated with the effect of PHEX protein on growth plates." (PMID 40331725, 2025). "Of these, DMP1 and PHEX are osteogenic marker genes, whose mutations result in hypophosphatemia, low bone mineral density, and elevated FGF23 production." (PMID 35392115, 2022). "XLH is the most common form of hereditary hypophosphatemia and is caused by inactivating mutations in the Phosphate Regulating Endopeptidase Homolog X-Linked (PHEX) gene." (PMID 35906684, 2022). "X-linked hypophosphataemia (XLH) is an X-linked dominant rare disease that refers to the most common hereditary hypophosphatemia (HH) caused by mutations in the phosphate-regulating endopeptidase homolog X-linked gene (PHEX; OMIM: * 300550)." (PMID 35251124, 2022). "X‐linked hypophosphatemia (XLH), the most common form of hereditary hypophosphatemia, is caused by disrupting variants in the PHEX gene." (PMID 34806794, 2022). "X‐linked hypophosphatemia (XLH), the most common form of hereditary hypophosphatemia, is caused by disrupting variants in the PHEX gene, located on the X chromosome." (PMID 34806794, 2022). "X‐linked hypophosphatemia rickets (XLH) is caused by inactivating mutations in the phosphate‐regulating endopeptidase homolog, X‐linked (PHEX) gene, leading to renal phosphate wasting and hypophosphatemia." (PMID 33869987, 2021). "X-linked hypophosphatemic rickets (XLH) is the first cause of inherited hypophosphatemia and is caused by mutation in the PHEX gene, resulting in excessive expression of the phosphaturic factor FGF23." (PMID 31151476, 2019). "Hypophosphatemia was further investigated with DNA sequencing, looking for a potential PHEX gene mutation." (PMID 22934198, 2012). "In summary, our studies indicate that PHEX mutations and the resulting hypophosphatemia may negatively affect the organic matrix deposited by odontoblasts during dentinogenesis." (PMID 32116788, 2020). "Our results support the hypothesis that hypophosphatemia resulting from PHEX loss-of-function affects the integrity of the organization of the dentin matrix and suggests that exogenous DMP1 can restore physiological processing of matrix proteins, in addition to its canonical role in mineralization." (PMID 32116788, 2020). "Disruption of the ECM components necessary for the template formation and mineralization of cartilage, bone, dentin, and cementum have been reported in the mouse model for XLH (PhexHyp mouse), suggesting that loss of PHEX function and/or hypophosphatemia may disrupt ECM deposition." (PMID 32116788, 2020). "Mutations in the PHEX gene are associated withincreased secretion of FGF-23 by osteocytes, inducing phosphate wasting, hypophosphatemia,impaired endochondral ossification, and alterations of bone matrix and mineralization thatpersist for life." (PMID 40215218, 2025). "To clarify, XLH is caused by a loss-of-function mutation in the phosphate-regulating endopeptidase homolog X-linked (PHEX) gene, which normally regulates FGF-23 production, leading to uncontrolled FGF-23 production and hypophosphatemia." (PMID 41583152, 2025). "It is characterized by a mutation of the PHEX gene which results in excess FGF23 production, with abnormal renal and intestinal phosphorus metabolism, hypophosphatemia and osteomalacia secondary to chronic renal excretion of phosphate." (PMID 38117452, 2024). "Recent researches have shown that the mineralization induced by human cells is disturbed independently of hypophosphatemia and supported a local role for PHEX, DMP1 or FAM20C in matrix mineralization." (PMID 36717535, 2023).
hypophosphatemia (continued). "Two third-generation siblings with skeletal dysplasia and hypophosphatemia harbored both COL2A1 and PHEX pathogenic variants which co-segregated with phenotypes across the paternal and maternal pedigrees." (PMID 37278761, 2023). "Mutations in PHEX, DMP1, and FAM20C have been reported to be responsible for FGF23-related hypophosphatemia." (PMID 36776964, 2023). "The PHEX gene is responsible for X-linked hypophosphatemic rickets (XLH), the most common form of hereditary hypophosphatemia." (PMID 35909535, 2022). "PHEX is expressed in osteocytes and odontoblasts, and loss-of-function PHEX mutation results in excess circulating fibroblast growth factor 23 (FGF23), leading to hypophosphatemia." (PMID 34141703, 2021). "The most common FGF23‐mediated hypophosphatemia is X‐linked hypophosphatemia (XLH), caused by mutations in the PHEX gene." (PMID 31485552, 2019). "Inactivating mutations within the PHEX gene are associated with increased circulating levels of FGF23 resulting in phosphaturia, hypophosphatemia, and impaired activation of 25-hydroxyvitamin D to 1,25 dihydroxy-vitamin D." (PMID 29460029, 2018). "Mutations in the PHEX gene occurring in X-linked hypophosphatemic rickets can cause a PHEX gene product to be unable to cleave FGF 23 leading to increased FGF 23, hypophosphatemia, and hyperphosphaturia." (PMID 22934198, 2012). "Loss-of-function mutations of the PHEX gene lead to the increase of circulating fibroblast growth factor 23 (FGF23), resulting in hypophosphatemia by reducing resorption of phosphate in the renal proximal tubule and synthesis of 1,25-dihydroxyvitamin D (1,25-(OH)2D3)." (PMID 40331725, 2025). "However, when we analyzed the relationship between PHEX activity and serum phosphorus level, we found that patients with low PHEX activity tended to have severe hypophosphatemia and high rickets severity score." (PMID 38442738, 2024). "XLH is an inherited disease of phosphate metabolism in which inactivating mutations of the Phosphate-Regulating Endopeptidase Homolog, X-Linked (PHEX) gene lead to local and systemic effects including hypophosphatemia, bone defects such as rickets and osteomalacia, and elevated levels of FGF23." (PMID 39666728, 2024). "Increased renal tubular loss of phosphorus is a cause of hypophosphatemia; it could be due to a tumor producing FGF-23 or a genetic disorder (XLH) caused by an inactivating mutation in the PHEX gene." (PMID 36382755, 2022). "Hypophosphatemia associated to urinary wasting of phosphate, relatively low values of 1,25-dihydroxyvitamin D and elevated alkaline phosphatase levels all support the diagnosis of XLH, confirmed by the mutation found in the PHEX gene." (PMID 32133333, 2020). "Recently, it has been shown in a human dental pulp cell model of extracellular mineralisation that there is likely also a role for impaired local intrinsic PHEX activity, as well as systemic hypophosphatemia, in the defective mineralisation of individuals with XLH." (PMID 29460029, 2018). "It is important to recognize FGF23-mediated persistent hypophosphatemia and its associated osteomalacia, irrespective of PHEX gene status, as it may be effectively managed with burosumab regardless of its underlying etiology." (PMID 41445556, 2025). "It is possible to carry rare variants of PHEX that have not yet been identified as pathogenic for FGF23-mediated hypophosphatemia, and the current genetic tests harbor limitations and may not detect all possible pathogenic genetic causes." (PMID 41445556, 2025). "In the hypophosphatemia genetic testing program, approximately 10% of clinically confirmed XLH patients had no variant identified in PHEX or in another gene, suggesting that up to 10% of clinical XLH patients may have an undetected PHEX variant." (PMID 34806794, 2022).
hypophosphatemia (continued). "The skeletal defects of the PHEX- and DMP1-deficient subjects are believed to be due to the combined effects of two factors: 1) the intrinsic defects of the PHEX- and DMP1-deficient cells that prevent them from forming and mineralizing ECM properly and 2) hypophosphatemia." (PMID 22615579, 2012). "The inactivation of PHEX/Phex or DMP1/Dmp1 has been shown to result in the increased expression of FGF23/Fgf23, leading to increased renal Pi wasting and hypophosphatemia in both humans and mice." (PMID 24710520, 2014). "Because PHEX, DMP1, and ENPP1 all induce FGF23-related hypophosphatemia, they may affect common pathophysiological mechanisms inducing enthesopathies and spinal ligament ossifications." (PMID 37530996, 2023).
rickets (30 papers, 2010 to 2025). Bone softening and weakening usually caused by deficiency or impaired metabolism of vitamin D. Deficiency of calcium, magnesium, or phosphorus may also cause rickets. "X-linked hypophosphatemic (XLH) is the most common inherited form of rickets, caused by inactivating mutations in the PHEX gene." (PMID 40980824, 2025). "Background/Objectives: X-linked hypophosphataemic rickets (XLH) represents the most frequent type of rickets from genetic origin, it is caused by mutations on the PHEX gene." (PMID 39795619, 2025). "The most common cause of inherited rickets is caused by X-linked dominant variants in the PHEX gene." (PMID 39659542, 2024). "In this study, we conducted an investigation on two patients diagnosed with rickets and identified a deletion mutation (c.1985delA) in the PHEX gene through whole-exome gene sequencing analysis." (PMID 38116308, 2023). "XLH is the most frequent form of inherited rickets in humans and is caused by inactivating mutations in the phosphate-regulating endopeptidase homolog X-linked (PHEX) gene." (PMID 36278488, 2022). "Presently, more than 500mutations in the PHEX gene have been found to causehypophosphatemic rickets." (PMID 32897287, 2021). "While the pathomechanism for rickets is well understood, the direct role of PHEX (Phosphate-regulating neutral endopeptidase) deficiency in non-rachitic features including complex deformities, skull and dental affections remains unclear." (PMID 35399930, 2022). "Other novel targets identified in this study include PHEX (phosphate‐regulating gene with homologies to endopeptidase on the X chromosome), an osteoblast-related gene that when inactive, leads to excessive phosphate wasting and consequently causes rickets." (PMID 34551771, 2021). "XLH is a disorder caused by phosphate regulating endopeptidase homolog X-linked (PHEX) gene mutations transmitted in an X-linked dominant manner, and is found in 80% of patients with inherited rickets/osteomalacia." (PMID 36060934, 2022). "Seven of the amelogenesis imperfecta-associated genes (CYP27B1, EPNN1, PHEX, SLC4A1, SLC4A4, VDR, and WDR72) are known to cause rickets when mutated." (PMID 33672174, 2021). "It should be highlighted that a high-phosphate supplement diet rescues rickets but not osteomalacia, similar to Hyp mice (the murine model of XLH that lacks the endopeptidase PHEX) and human vitamin D–resistant rickets." (PMID 34360805, 2021). "Although the exact mechanism of how PHEX mutations cause rickets/osteomalacia remains unknown, some studies have shown that PHEX may inactivate bone mineralization inhibitors and that one of the extraosseous consequences of PHEX inactivation includes an increase in the level of FGF-23." (PMID 24836714, 2014). "These molecular defects cause abnormal functions of the cartilage extracellular matrix (COMP), paracrine signalling factors (PHEX, FGFR3-related rickets), transcriptional regulation (LZTR1), histone methylation (KMT2A), posttranslational modification (NAA15), and mtDNA replication and repair (POLG)." (PMID 39415983, 2024). "Therefore, we performed mutational screening of the PHEX promoter region and other genes responsible for FGF23-related rickets; this analysis identified no mutations, so we concluded that the p.Gly316Val mutation is likely to be causative of XLH." (PMID 25861491, 2015).
hypophosphatemic rickets (29 papers, 2012 to 2026). Rickets due to low serum phosphate concentrations, the cause of which can be nutritional or genetic. "Using next-generation sequencing, we identified a novel mosaic nonsense variant in the PHEX gene on the X chromosome—c.1971C > A, p.(Tyr657X)—in a man with clinical features of hypophosphatemic rickets." (PMID 40533633, 2025). "In conclusion, we have identified a novel mosaic nonsense variant in the PHEX gene on the X chromosome—c.1971C > A, p.(Tyr657X)—due to apparent postzygotic mutation in a man with the clinical syndrome of hypophosphatemic rickets." (PMID 40533633, 2025). "Most commonly, hypophosphatemic rickets is caused by pathogenic variants in the X-chromosomal PHEX gene, but autosomal dominant and recessive forms also exist." (PMID 39877728, 2025). "We identified a novel mosaic nonsense variant in the PHEX gene on the X chromosome by next-generation sequencing—c.1971C > A, p.(Tyr657X)—–in a man with clinical features of hypophosphatemic rickets." (PMID 40533633, 2025). "XLH is the most common form of hereditary hypophosphatemic rickets and is caused by inactivating mutations in the PHEX gene." (PMID 36246908, 2022). "Four patients had causative mutations in the CLCN5, OCRL genes, which are associated with Dent disease, and a heterozygous mutation of the PHEX gene was detected in a patient diagnosed with XLH." (PMID 35612621, 2022). "In this report, we describe a patient with hypophosphatemic rickets as result of anovel likely pathogenic variant in PHEX gene." (PMID 32897287, 2021). "Hypophosphatemic rickets (HR) is a rare renal phosphate-wasting disorder, which is usually X-linked and is commonly caused by PHEX mutations." (PMID 31514490, 2020). "PHEX indirectly regulates FGF23, and PHEX gene mutation causes hypophosphatemic rickets, a rare hereditary bone disease." (PMID 32733380, 2020). "In hypophosphatemic rickets, renal proximal tubular resorption is compromised due to mutations in PHEX gene which is a phosphate-regulating gene." (PMID 27340574, 2016). "The aim of this study was to identify PHEX gene mutations and describe the clinical features observed in 6 unrelated Chinese families and 3 sporadic patients with hypophosphatemic rickets/osteomalacia." (PMID 24836714, 2014). "The PHEX mutations were detected in 6 familial and 3 sporadic hypophosphatemic rickets/osteomalacia." (PMID 24836714, 2014). "In this study, we identified PHEX gene mutations in Chinese patients (familial and sporadic) with hypophosphatemic rickets/osteomalacia in order to elucidate the PHEX gene mutation types and clinical features observed in Chinese patients." (PMID 24836714, 2014). "Additionally, another homozygous missense mutation (c.10G>C) in exon 1 of PHEX was identified, which is typically linked to hypophosphatemic rickets." (PMID 38057384, 2023). "Phosphopenic rickets may be caused by mutations in the PHEX gene(phosphate regulating endopeptidase homolog X-linked)." (PMID 32897287, 2021). "PHEX or DMP1 mutations cause hypophosphatemic-rickets and altered energy metabolism." (PMID 24839967, 2014). "Hypophosphatemic rickets, a metabolic bone disorder mainly caused by a mutation in the PHEX (phosphate-regulating endopeptidase X-linked) gene, leads to skeletal deformities, growth retardation, and dental problems, affecting all ages and genders." (PMID 38929327, 2024). "Pathogenic variants in the PHEX gene cause rare and severe X-linked dominant hypophosphataemia (XLH), a form of heritable hypophosphatemic rickets (HR) characterized by renal phosphate wasting and elevated fibroblast growth factor 23 (FGF23) levels." (PMID 37568915, 2023). "Osteocytes also express PHEX, DMP1, ENPP1, and FAM20C, and inactivating mutations cause FGF23-related hypophosphatemic rickets/osteomalacia." (PMID 36246908, 2022).
hypophosphatemic rickets (continued). "For example, inactivating mutations in the phosphate-regulating endopeptidase homolog, X-linked (PHEX) gene lead to the upregulation of FGF23 production in patients with XLH, which is the most prevalent form of genetic FGF23-related hypophosphatemic rickets." (PMID 30627598, 2019). "Mutations in four genes, FGF23 itself, PHEX, DMP1 and ENPP1, have been reported to remarkably increase the plasma levels of FGF23, leading to hereditary hypophosphatemic rickets." (PMID 22615579, 2012). "While likely to also exist in children with hypophosphatemic rickets due to PHEX mutations, this has not been reported, probably due to limited access to samples; here mouse models provide useful insights." (PMID 38315213, 2024). "Osteocytes express FGF23 and other multiple genes responsible for hereditary hypophosphatemic rickets, which include phosphate-regulating gene homologous to endopeptidase on X chromosome (PHEX), dentin matrix protein 1 (DMP1), and family with sequence similarity 20, member C (FAM20C)." (PMID 36246908, 2022). "In addition, some molecules responsible for hereditary hypophosphatemic rickets, such as PHEX and DMP1, are also highly expressed in osteocytes." (PMID 24710520, 2014). "It is possible that other unidentified factors may contribute to the severity of hypophosphatemic rickets independent of PHEX gene alteration." (PMID 38442738, 2024).
X-linked hypophosphatemic rickets (19 papers, 2011 to 2026). "We report a rare case of a 60-year-old male patient with X-linked hypophosphatemic rickets (XLH) caused by a PHEX gene mutation complicated with polyostotic fibrous dysplasia (FD)." (PMID 41928886, 2026). "X-linked hypophosphatemic rickets (XLH) is a rare monogenic disorder caused by loss-of-function mutations at the PHEX gene (Xp22.11), which encodes for the zinc-dependent phosphate-regulating endopeptidase homolog, X-linked (PHEX)." (PMID 37109242, 2023). "X-linked hypophosphatemic rickets (XLH) is a genetic disorder associated with mutations in the Phosphate Regulating Endopeptidase Homolog X-Linked (PHEX) gene." (PMID 32547492, 2020). "X-linked hypophosphatemic rickets (XLH) (OMIM 307800) is a rare disease caused by mutations in the PHEX gene." (PMID 31151476, 2019). "PHEX mutations are associated with X-linked hypophosphatemic rickets in human patients, with hearing loss as one of the symptoms." (PMID 27959908, 2016). "This is consistent with previous studies that show phosphorylation of the ASARM-motif is important for specific interaction, binding and substrate hydrolysis by PHEX, a Zn-metalloendopeptidase responsible for X-linked hypophosphatemic rickets." (PMID 24839967, 2014). "PHEX, another potent mediator of phosphate homeostasis, has been identified from analyses of human X-linked hypophosphatemic rickets (XLH) and Hyp mutant models." (PMID 21854633, 2011). "Inactivating mutations in the phosphate-regulating gene with homologies to endopeptidases on the X chromosome (PHEX) cause X-linked hypophosphatemic rickets (OMIM 307800), and loss of DMP1 activity results in autosomal-recessive hypophosphatemic rickets (OMIM 241520)." (PMID 22615579, 2012). "X-linked hypophosphatemic rickets (XLH) is a rare genetic disorder with a frequency of 1:20,000, caused by mutations in the PHEX gene, resulting in impaired phosphate metabolism and bone mineralization." (PMID 40843893, 2025). "Studies into rare genetic disorders, such as X-linked hypophosphatemic rickets (XLH), have identified a family of proteins, FGF23, PHEX, and MEPE which act through a bone-kidney axis to modulate phosphate homeostasis and thus bone mineralization indirectly." (PMID 22766095, 2012). "While humans with a PHEX mutation, leading to X-linked hypophosphatemic rickets (XLH), have not been reported to be at higher risk of developing diabetes, this may have been understudied as XLH is very rare." (PMID 38577264, 2024).